TLR9 (toll like receptor 9)
Diseases named in the same sentence as TLR9 in open-access papers (continued):
Sharing a sentence is not in itself a finding about the gene and the disease.
head and neck cancer (7 papers, 2014 to 2025). A primary or metastatic malignant neoplasm affecting the head and neck. "Association between TLR9 and HPV has been shown in previous studies, where impaired expression and function of TLR9 was observed in cervical and in head and neck cancers." (PMID 39644451, 2024). "Re-introducing TLR9 under the control of an exogenous promoter in cervical or head and neck cancer patient-derived cells reduced cell proliferation, colony formation and prevented independent growth of cells under soft agar." (PMID 27454079, 2016). "We show for the first time that TLR9 per se in head and neck cancer cells was able to slowdown the cell cycle during the S-phase." (PMID 27454079, 2016). "Re-constitution of TLR9 expression in head and neck cancer cells lengthened the S-phase of the cell cycle as well as increase p16INK4a stability." (PMID 27454079, 2016). "The increase of p21WAF1 due to TLR9 re-expression was also observed in our model of head and neck cancer (also upregulated in our microarray data: Series record GSE78858)." (PMID 27454079, 2016). "Herein, we utilized an NHRI-NH1 cell line-based syngeneic orthotopic head and neck cancer animal model to investigate the efficacy and functional mechanism of a combinational therapy involving TLR9 activator (CpG-2722) and PS-targeting cytotoxic prodrug (BPRDP056)." (PMID 37324949, 2023). "TLR9 overexpression in head and neck cancer cells also prevented colony formation under soft agar." (PMID 27454079, 2016). "Therefore, the cell cycle length in the head and neck cancer cell line 136 post TLR9 induction was analyzed after cell synchronization using thymidine double blockage." (PMID 27454079, 2016). "We next determined whether restoring TLR9 expression would have an effect on cell growth in head and neck cancer cells." (PMID 27454079, 2016). "Herein, we investigated the effectiveness and mechanism of a combination therapy involving TLR9 activator (CpG-2722) and phosphatidylserine (PS)-targeting prodrug of SN38 (BPRDP056) in a syngeneic orthotopic head and neck cancer animal model." (PMID 37324949, 2023). "We chose the head and neck cancer cell lines (HNSCC) 124 and 136 to generate TLR9-expressing clones." (PMID 27454079, 2016). "We observed that as well as in viral induced cancers, we demonstrated in patients with head and neck cancer (that are HPV negative) that TLR9 levels were downregulated." (PMID 27454079, 2016). "In head and neck cancer patients weak or no TLR9 staining was observed." (PMID 27454079, 2016).
injury (7 papers, 2015 to 2024). Damage inflicted on the body as the direct or indirect result of an external force, with or without disruption of structural continuity. "Reduced renal IL-1β levels were in concordance with a previous study where TLR9 deficiency reduced the expression of IL-1β in a model of acetaminophen-induced liver injury." (PMID 26361210, 2015). "Our in vitro results lead us to propose PINK1-mediated mitophagy with mtDNA release as a therapeutic target via TLR9/MyD88 signaling in mechanical stretching-induced acute lung injury." (PMID 33015037, 2020). "We then used the established TLR9-dependent model of acetaminophen (APAP)-induced liver injury (DILI) to further evaluate the potential function of PI3Kγ in TLR9 activated tissue injury." (PMID 31836766, 2019). "Other inflammation signals, including toll-like receptor 9 (TLR9) signal and cyclic adenosine monophosphate/protein kinase A (cAMP/PKA) signal, were observed in ischaemic cortex after cerebral ischaemia and reperfusion and acute lung injury." (PMID 34938814, 2021).
meningitis (7 papers, 2007 to 2024). A disorder characterized by acute inflammation of the meninges of the brain and/or spinal cord. "Subsequent comparative analyses in an experimental meningitis model, however, implicated the concerted action of TLR2 and TLR4, while negating a role for TLR9 in the innate immunological perception of pneumococcal CNS infection." (PMID 38358825, 2024). "Three types of Toll-like receptors (TLR2, TLR4, TLR9) have been identified as the ones that are involved in S. pneumoniae meningitis." (PMID 39121090, 2024). "Three days prior to the induction of meningitis by intracerebral injection of S. pneumoniae D39, wild-type and Toll-like receptor (TLR9)−/− mice received an intraperitoneal injection of 100 μg CpG ODN or vehicle." (PMID 33531028, 2021). "Carriers of the TLR9 + 2848 mutant genotype have a lower chance of developing meningitis when colonized with N. meningitidis." (PMID 22577991, 2012). "Bacterial DNA can initiate an innate immune response via Toll-like receptor 9 (TLR9) potentially leading to septic shock, septic arthritis, or meningitis." (PMID 17925007, 2007). "TLR4+896 mutants are highly associated with post-meningitis hearing loss and combined carriership of the TLR2+2477 WT with TLR4+896 mutant alleles as well as the combination of TLR4+896 mutant alleles with TLR9 -1237 mutant alleles significantly increases this risk." (PMID 22662111, 2012). "A previous study has shown enhanced neuroinflammation following TLR9 agonist administration and suggested a role of normal TLR7, and potentially TLR 8 signaling, in modulating TLR9 related meningitis and neuroinflammation." (PMID 25229618, 2014).
renal fibrosis (7 papers, 2011 to 2025). A final common manifestation of a wide variety of chronic kidney diseases characterized by glomerulosclerosis and tubulointerstitial fibrosis. "Previous studies demonstrated that the activation of the TLR/MyD88/NF-κB signaling pathway was intimately associated with the development of renal fibrosis, and that renal fibrosis and damage in the LN mouse model could be mitigated by inhibiting the TLR9/MyD88/NF-κB signaling pathway." (PMID 40593236, 2025). "Our results suggest that HCQ inhibits macrophage activation and MAPKs via the TLR-9 pathway, thereby attenuating renal fibrosis after IRI." (PMID 33936063, 2021). "In the present study, we first identified that HCQ served as a TLR-9 inhibitor and inhibited the activation of macrophages, thereby attenuating renal fibrosis post-IRI." (PMID 33936063, 2021). "The effects of HCQ on renal fibrosis and macrophages decreased after depletion of TLR-9 in vivo and in vitro." (PMID 33936063, 2021). "Likewise, activation of the NLR family pyrin domain containing 3 (NLRP3) and toll-like receptor 9 (TLR9) regulate macrophage polarization and renal fibrosis in different preclinical models." (PMID 38201227, 2023). "However, the effects of HCQ on renal fibrosis or activation of macrophages decreased after TLR-9 depletion." (PMID 33936063, 2021). "Previous results indicated that the effects of HCQ on renal fibrosis may have relied on the inhibition of TLR-9; therefore, a TLR-9 KO mouse was constructed." (PMID 33936063, 2021). "Taking into account that TLR-9 is involved in the development of renal fibrosis and serves as a potential therapy target for CKD, we investigated whether HCQ could attenuate CKD via TLR-9 signal pathway." (PMID 33936063, 2021). "Because HCQ attenuates renal fibrosis and inhibits activation of macrophages, we hypothesized that the effects of HCQ on renal tubulointerstitial fibrosis mainly rely on TLR-9." (PMID 33936063, 2021). "HCQ treatment attenuated renal fibrosis following renal injury in vivo, whereas the effects of HCQ could be terminated by depletion of TLR-9." (PMID 33936063, 2021). "These rather unexpected results are in accordance with the recent work of Anders's group showing that post obstructive renal fibrosis is independent of TLR2, TLR9 and MyD88." (PMID 24498450, 2014). "We therefore conclude that SIGIRR is redundant in UUO-induced renal fibrosis because TLR2-, TLR9- and MyD88 signaling do not significantly contribute to this model." (PMID 21544241, 2011). "Expression of TLR-9 but not TLR-7 in renal tissue post-IRI was inhibited by HCQ, and the results are consistent with our previous study showing that depletion of TLR-9 attenuated renal fibrosis." (PMID 33936063, 2021). "In vivo and in vitro results suggest that the effects of HCQ on macrophages and renal fibrosis decreased after depletion of TLR-9, and HCQ could not attenuate renal fibrosis post-IRI in the KO group." (PMID 33936063, 2021).
vasculitis (7 papers, 2008 to 2022). "TLR9 stimulation has also been reported to accelerate the activation, adhesion and degranulation of polymorphonuclear leucocytes (PMNs) in PR3‐ANCA vasculitis." (PMID 34626000, 2021). "In addition, HMGB1 enhanced the TLR9 levels and proliferation of B cells in plasma cells from PBMC of patients with AAV, and the latter was positively correlated with Birmingham vasculitis activity score." (PMID 35250993, 2022).
allergic bronchopulmonary aspergillosis (6 papers, 2015 to 2025). Allergic bronchopulmonary aspergillosis (ABPA) is a rare immunologic pulmonary disorder caused by hypersensitivity to Aspergillus fumigatus, clinically manifesting with poorly controlled asthma and recurrent pulmonary infiltrates. "Moreover, allele C on T-1237C (TLR9) was associated with susceptibility to allergic bronchopulmonary aspergillosis." (PMID 33777838, 2021). "In addition, TLR9(T1237C) also had increased prevalence in allergic bronchopulmonary aspergillosis, while TLR4(Asp299Gly) had significant association with chronic cavitary pulmonary aspergillosis." (PMID 26361369, 2015). "TLR9 mutation rs5743836 (in the promoter region) is linked to the development of allergic bronchopulmonary aspergillosis (ABPA)." (PMID 41295183, 2025). "Interestingly, among the European–American population, TLR9 rs5743836 (T1237C) was closely associated with bronchial asthma and an increased prevalence of TLR9 (T1237C) in allergic bronchopulmonary aspergillosis." (PMID 40149591, 2025). "Interestingly, TLR2 SNPs showed no susceptibility to CCPA but a potentially protective role in allergic bronchopulmonary aspergillosis (ABPA), whereas patients suffering from ABPA had significantly higher frequency of a TLR9 SNP (T-1237C) compared to unaffected controls." (PMID 25420452, 2015).
amyloid (6 papers, 2012 to 2025). "Conversely, our data clearly demonstrates that stimulation of innate immunity with TLR9 agonist CpG ODN can reduce both amyloid and tau related pathologies." (PMID 25178404, 2014). "In our initial studies, we utilized type B CpG ODN to stimulate innate immunity via TLR9 in the Tg2576 AD mouse model and showed this to be highly effective at reducing parenchymal and vascular amyloid burden, correlating with behavioral improvements." (PMID 25178404, 2014). "Recently, we have shown that TLR9 stimulation with CpG in 3xTg AD mice with both amyloid plaque and NFT pathology greatly reduces both of these pathologies in association with cognitive benefits." (PMID 24223593, 2013). "Stimulation of microglial activity via induction of Toll-like receptor 9 (TLR9) has also been shown to greatly reduce amyloid load and improve cognition." (PMID 22844635, 2012). "It is known that, modulation of TLR9 function, via CpG ODN agonists, showed amelioration of CAA levels, cortical amyloid burden in association with behavioral improvements in animal models of AD, with a non-negligible safety profile in non-human primate model of sporadic AD pathology." (PMID 37433968, 2023).
bacteremia (6 papers, 2011 to 2019). "We propose that TLR9 -1237 and +2848 polymorphisms have a beneficial effect on preventing bacteremia and increase the leukocyte influx in the CNS, reflecting an enhanced immune response inside the CNS." (PMID 22577991, 2012). "We associated TLR9 polymorphisms with prevention of bacteremia and higher levels of leukocytes in the CSF." (PMID 22577991, 2012). "TLR9-/- mice were found to be susceptible to meningococcal sepsis due to high bacteremia." (PMID 28052108, 2017). "A decreased incidence of positive blood cultures in children carrying TLR9 -1237 C allele and TLR9 +2848 AA genotypes may represent a reduction in the occurrence of secondary bacteremia due to more pronounced host immune response in the CSF." (PMID 22577991, 2012). "In a mouse meningococcal bacteremia model the role of TLR9 in preventing bacteremia was also confirmed." (PMID 22577991, 2012). "So children with TLR9 SNPs may have a lower chance to develop bacteremia because of the adequate but balanced bactericidal effects and higher chance of developing seizures due to the excessive inflammation associated brain damage in the CNS." (PMID 28202935, 2017). "For TLR9 rs352139, genotype AA and minor allele A were significantly higher in BM patients with bacteremia compared to those without (41.5% and 66.9% vs. 30.3% and 55.3%; P = 0.016 and P = 0.024)." (PMID 28202935, 2017). "For TLR9 rs352140, genotype TT and minor allele T were significantly lower in BM patients with bacteremia compared to those without (7.7% and 33.1% vs. 19.7% and 44.1%; P = 0.020 and P = 0.033)." (PMID 28202935, 2017). "TLR9 KO mice displayed reduced survival and elevated levels of bacteremia compared to WT mice." (PMID 22577991, 2012). "However, deletion of the TLR9 gene prevented only the bacteremia (P<0.05), but not animal survival (P = 0.107), compared with the irinotecan-injected WT mice." (PMID 26440613, 2015). "Thus, in case of a bacterial sepsis, the inflammatory response in the lung will never be induced by exclusive activation of TLR2 or TLR4 but always by costimulation of TLR9." (PMID 21547259, 2011).
Chagas disease (6 papers, 2010 to 2021). A parasitic infection caused by Trypanosoma cruzi. "In parallel, T. cruzi-glycosylphosphatidylinositol membrane anchor is recognized by both, TLR-2 and TLR-9, and exert a role in the prognosis of asymptomatic and cardiac clinical forms of Chagas disease." (PMID 34113663, 2021). "On the other hand, patients with different clinical manifestations of Chagas disease showed similar mRNA expression levels of TLR1, TLR3, TLR4, TLR5, TLR6, TLR7 and TLR9." (PMID 30044791, 2018). "Patients with different clinical manifestations of Chagas disease showed similar expression of TLR1, TLR3, TLR4, TLR5, TLR6, TLR7 and TLR9 mRNA." (PMID 30044791, 2018). "TLRs are involved in both protection against and the pathology of Chagas disease, and among these receptors, it is estimated that TLR2, TLR4, and TLR9 are the most important." (PMID 25371910, 2014). "Recently, we reported that TLR2, TLR4 and TLR9 are differentially modulated in injured livers from BALB/c and C57BL/6 (B6) mice during Trypanosoma cruzi infection." (PMID 21072226, 2010). "Concerning Trypanosoma cruzi, the agent of Chagas disease, we have previously characterized glycosylphosphatidylinositol (GPI) anchored mucin-like glycoproteins (tGPI-mucin) and unmethylated CpG DNA sequences as TLR2 and TLR9 agonists, respectively." (PMID 23650544, 2013).
Cirrhosis (6 papers, 2016 to 2025). A chronic disorder of the liver in which liver tissue becomes scarred and is partially replaced by regenerative nodules and fibrotic tissue resulting in loss of liver function. "In summary, polymorphisms in TLR-2, TLR-4 and TLR-9 genes are associated with an increased bacterial antigen burden and a deficient pro-inflammatory cytokine response in patients with cirrhosis." (PMID 28418003, 2017). "We have evaluated the effect of TLR2 rs4696480, TLR4 rs4986790 and TLR9 rs187084 polymorphisms in the bacterial antigen load and the pro-inflammatory mediator levels in the blood of a consecutive series of patients with cirrhosis and AF." (PMID 28418003, 2017). "We evaluated the incidence of 3 well-known polymorphisms in TLR-2, TLR-4 and TLR-9 in patients with cirrhosis." (PMID 28418003, 2017). "The aim of the present study was to evaluate the incidence of relevant polymorphisms in TLR-2, TLR-4 and TLR-9, specific receptors of bacterial products which are frequently translocated from the gut in patients with cirrhosis." (PMID 28418003, 2017). "In one study, the bacterial DNA sensing receptor in neutrophils, TLR9, has been shown to be more highly expressed in neutrophils from patients with cirrhosis than healthy controls." (PMID 37822786, 2023). "Memory B cells were chronically activated in advanced cirrhosis, as memory B cells in advanced cirrhosis were more easily activated by TLR9 plus elevated PAMP levels in cirrhotic conditions." (PMID 34248941, 2021). "Consecutive patients with cirrhosis and ascitic fluid were distributed by TLR2 rs4696480, TLR4 rs4986790, and TLR9 rs187084 single-nucleotide polymorphisms." (PMID 28418003, 2017). "High expression levels of TLR7 and TLR9 have been observed in liver tissue microarrays of patients with cirrhosis, viral hepatitis, and hepatocellular cancer." (PMID 27456065, 2016). "However, in other studies, TLR9 has not been found to be upregulated in patients with cirrhosis and circulating bacterial DNA measured in the plasma of patients with cirrhosis could neither be associated with the changes in neutrophil phagocytic and basal ROS production, nor with patient mortality." (PMID 37822786, 2023).
co-infection (6 papers, 2012 to 2025). "Mutation presented in at least one allele of the TLR9 2848C/T single nucleotide polymorphism (SNP) was associated with the occurrence of CMV DNAemia among HIV-infected patients with CMV co-infection (p = 0.004)." (PMID 34572011, 2021). "A role of SR-A has also been shown in the context of viral-bacterial co-infection, in which TLR9 acts as a negative regulator." (PMID 40980882, 2025). "This TLR9 SNP also showed a higher rate of occurrence of viral co-infection even after Bonferroni correction for multiple testing (pc = 0.017) in the unadjusted model." (PMID 34572011, 2021). "One possible reason for the reduced TLR2 and TLR9 in our participants with TB/HIV coinfection could be that HIV diminishes TLRs expression and functionality." (PMID 38660059, 2024). "Given the direct and indirect effects of HIV on TLR9, it is possible that, in the setting of HIV-HBV coinfection, TLR9 signalling in the liver by both HIV and HBV could result in an increase in chemokine production and a proinflammatory response." (PMID 22474436, 2012). "Interestingly, PDCoV/PEDV co-infection showed a transient up-regulatory effect on TLR7, TLR8, and TLR9 by 3 DPI." (PMID 36376395, 2022). "The earlier up-regulatory effect of PEDV/PDCoV co-infection in the expression levels of TLR7, TLR8, and TLR9, as compared with the single-infection groups, support our hypothesis concerning the potential synergistic effect." (PMID 36376395, 2022). "Finally, subjects with latent TB and filarial coinfection have been shown to exhibit decreased toll-like receptor 2 (TLR2) and toll-like receptor 9 (TLR9) expression, which was reversed after successful antifilarial chemotherapy." (PMID 25632943, 2015). "However, studies focusing on the effect of TLR9 SNPs on HIV/CMV co-infection and CMV replication in adult subjects are lacking." (PMID 34572011, 2021).
dilated cardiomyopathy (6 papers, 2014 to 2024). Cardiomyopathy which is characterized by dilation and contractile dysfunction of the left and right ventricles. "In thoracic transverse aortic constriction induced cardiomyopathy, mtDNA is capable of inducing dilated cardiomyopathy through TLR9 signaling." (PMID 38790051, 2024). "Finally, we investigated the SIRT3-dependent mitochondrial increases of TLR9 by empagliflozin in subjects with dilated cardiomyopathy (DCM)." (PMID 33138323, 2020). "The dilated cardiomyopathy patient with SIRT3 point mutation and reduced enzymatic activity is associated with reduced TLR9 activation and the absence of mitochondrial responses in the heart after the SGLT2 inhibitor treatment." (PMID 33138323, 2020).